JAK1 (Janus kinase 1)
Diseases named in the same sentence as JAK1 in open-access papers (continued):
Sharing a sentence is not in itself a finding about the gene and the disease.
diabetic kidney disease (11 papers, 2019 to 2025). Progressive kidney disorder caused by vascular damage to the glomerular capillaries, in patients with diabetes mellitus. "A reduction in albuminuria was noted in participants with diabetic kidney disease in a phase 2 trial of the JAK1/JAK2 inhibitor baricitinib." (PMID 33343569, 2020). "In humans with advanced diabetic kidney disease, 24 weeks of JAK1/2 inhibition with baricitinib reduced albuminuria by 41% while also reducing circulating levels of SAA and other inflammatory biomarkers.." (PMID 30763329, 2019). "Similarly, treatment with a specific JAK1/2 inhibitor for 2 weeks partly reversed the major phenotypic changes of diabetic kidney disease." (PMID 34798872, 2021). "Induced expression of JAK2 worsens diabetic kidney disease (DKD) in experimental mice, and the JAK1/JAK2 inhibitor baricitinib is highly effective in DKD." (PMID 34067609, 2021). "In fact, a phase 2 clinical trial demonstrated that the small molecule baricitinib, a selective JAK1 and JAK2 inhibitor, effectively lowered albuminuria in patients with type 2 diabetes and diabetic kidney disease." (PMID 41474553, 2025). "In a clinical study on patients with Diabetic kidney disease (DKD), researchers investigated the role of JAK1 and JAK2 in DKD onset and progression." (PMID 37701031, 2023). "The JAK1/JAK2 inhibitor protects autoimmune diabetes in experimental mice and improves the condition of diabetic kidney disease." (PMID 34067609, 2021). "JAK1 and JAK2 inhibition by Bariticinib decreases albuminuria levels in patients with diabetic kidney diseases (DKD)." (PMID 34093584, 2021).
glioblastoma (11 papers, 2011 to 2025). The most malignant astrocytic tumor (WHO grade IV). "It has been reported that silencing HDAC7 in glioblastoma (GMB) cell U87 enhanced STAT3 phosphorylation by upregulating JAK1 expression." (PMID 29126425, 2017). "In malignant glioblastoma cell lines, the levels of phosphorylated JAK1, JAK2, and STAT3 were uniformly upregulated with FAK and positively correlated, followed by the levels of phosphorylated p38, JNK and ERK1/2 downregulated, and the trend was reversed after treatment." (PMID 38240856, 2024). "It has been proposed that tumor-associated mesenchymal stem-like cells could play an important role in glioblastoma ECM remodeling through CCL2/JAK1/MLC2 signaling." (PMID 36980765, 2023). "First, to investigate whether STAT3 and upstream kinases JAK1/2 are activated in U251 cells, we performed western blot and showed a higher expression of pSTAT3 Tyr705 and pJAK2 in the glioblastoma cell line U251 than in NHA." (PMID 21906308, 2011). "The co-inhibition of Notch1 and JAK1/STAT3 has also been shown to disrupt the proliferation, migration, and invasion of glioblastoma cells and to inhibit the epithelial–mesenchymal transition." (PMID 40019515, 2025). "According to a study, cucurbitacin I markedly decreased p-JAK1, p-JAK2, p-STAT3, and p-STAT5 levels and inhibited proliferation of glioblastoma cells." (PMID 36193062, 2022). "g., IFNGR1, JAK1, and JAK2) made glioblastoma cells more resistant to CAR T cells both in vitro and in vivo." (PMID 36389701, 2022). "Using the published single-cell datasets, we also observed the positive correlation of STING and JAK1 expression in vascular endothelial cells from patients with PCa, COAD, GC, primary liver cancer (PLC), glioblastoma (GM), glioblastoma multiforme (GBM), and upper tract urothelial carcinoma (UTUC)." (PMID 39817453, 2025).
graft versus host disease (11 papers, 2018 to 2025). An immune system disorder that occurs after allogeneic hematopoietic stem cell transplant and is a reaction of donor immune cells against host tissues. "In addition, itacitinib, which is a selective JAK1 inhibitor developed for the treatment of graft-versus-host disease, may resolve CRS with a lower risk of immunosuppression." (PMID 34794490, 2021). "Itacitinib is a new oral selective JAK1 inhibitor that was authorized by the EMAAVCI in 2018 as an orphan medication to treat graft versus host disease." (PMID 41153712, 2025). "Ruxolitinib is an oral JAK1/2 inhibitor approved for the treatment of polycythemia vera, myelofibrosis, vitiligo, and steroid-refractory graft-versus-host disease (SR-GVHD)." (PMID 37492565, 2023). "Ruxolitinib is an orally bioavailable JAK1/2 inhibitor that functions by inhibiting STAT3 phosphorylation and is approved by the U.S. Food and Drug Administration (FDA) for treating steroid refractory graft-versus-host-disease, myelofibrosis, and polycythemia vera." (PMID 38339245, 2024). "Therefore, IFN-γR signaling is emerging as an attractive target for graft-versus-host disease (GVHD) intervention, as corroborated by clinical results using the nonselective JAK1/2 inhibitor ruxolitinib (Rux) and preclinical results with barcitinib." (PMID 36445781, 2023).
Pruritus (11 papers, 2018 to 2025). Pruritus is an itch or a sensation that makes a person want to scratch. "The underlying mechanism of pruritus in LP remains unknown; however, similar responses were seen with topical JAK1/2 inhibition with topical ruxolitinib, implying that JAK1 and/or JAK2 play a central role in LP pruritus." (PMID 39541169, 2024). "Joo Kwon retrospectively reviewed the medical records of DEB patients with refractory pruritus who were treated with either baricitinib, a JAK1/2 inhibitor, or upadacitinib, a selective JAK1 inhibitor." (PMID 38968458, 2024). "Cytokines including IL-31, IL-4, IL-13, and TSLP are crucial for pruritus in AD transmit their signals into the cells via JAK-1 and JAK-2." (PMID 36983094, 2023). "To further investigate the anti-pruritus mechanisms underlying HLJDT, we analyzed pruritus-related markers (i.e., JAK1, HRH4, IL-4αR, GRP, SP, and TRPV-1) from the dorsal root ganglion." (PMID 34925005, 2021). "Previous studies have indicated that IL-31, IL-4Rα, JAK1, and HRH4 are strongly associated with pruritus in AD." (PMID 34970141, 2021). "The mRNA expression levels of all pruritus-related markers, except JAK1, were significantly upregulated in the model group, which were downregulated by 12.8 g/kg HLJDT." (PMID 34925005, 2021). "In humans, tofacitinib, a JAK-1/3 inhibitor, significantly reduced pruritus in chronic idiopathic pruritus patients, who also favorably respond to phototherapy." (PMID 30560129, 2018). "The authors concluded that IL-4, via neuronal JAK-1, is an important mediator of chronic pruritus as it “sensitizes” pruriceptive sensory nerves and lowers the threshold for other prurigenic mediators to induce itch." (PMID 30560129, 2018). "It has results suggest that JAK1 or JAK1/2 inhibitors could be a promising treatment option for DEB-related pruritus." (PMID 38968458, 2024). "Twenty-seven dogs were treated with either oclacitinib, a Janus Kinase (JAK) inhibitor that primarily targets JAK1-dependent signaling pathways (n = 17), or lokivetmab, a caninized monoclonal antibody that targets interleukin-31, a cytokine that induces pruritus in dogs (n = 10)." (PMID 34677385, 2021). "The oral JAK1 inhibitor upadacitinib might suppress the effects of IL-31 or IL-4/IL-13 and block the communication between nerves and eosinophils, leading to the suppression of pruritus." (PMID 36983203, 2023). "Furthermore, upadacibitinib, an oral JAK-1 inhibitor, has effectively reduced pruritus in AD." (PMID 36983094, 2023). "JAK1 inhibition represents a good therapeutic strategy for patients suffering from significant pruritus and patients with an intense itch that does not respond to IL-4 receptor inhibitors, IL-13 inhibitors, and IL-31 receptor inhibitors." (PMID 36839707, 2023). "Though only tested in adults so far, topical JAK1/JAK3 inhibitor tolfacitinib was better than vehicle alone in a phase IIa clinical trial across all endpoints (Eczema Area and Severity Index [EASI], Investigator’s Global Assessment Score [IGA], body surface area and pruritus; p < 0.001)." (PMID 31694234, 2019).
ankylosing spondylitis (10 papers, 2018 to 2025). An autoimmune chronic inflammatory disorder characterized by inflammation in the vertebral joints of the spine and sacroiliac joints. "Ivarmacitinib (SHR0302), a selective Janus kinase 1 inhibitor, has demonstrated substantial improvements in patients with active ankylosing spondylitis (AS)." (PMID 41357869, 2025).
herpes zoster (10 papers, 2019 to 2026). A common dermal and neurologic disorder caused by reactivation of the varicella-zoster virus that has remained dormant within dorsal root ganglia, often for decades, after the patient's initial exposure to the virus in the form of varicella (chickenpox). "JAK1,2,3 inhibitors have also been associated with increased risk of serious infections, including herpes zoster." (PMID 39403378, 2024). "We confirmed several previously recognized AEs related to oral JAK-1 inhibitors in AD treatment, including herpes zoster, eczema herpeticum, and influenza." (PMID 41255603, 2025). "Baricitinib is also linked to a higher incidence of adverse events, particularly herpes zoster, due to its inhibition profile targeting JAK1 and JAK2." (PMID 39610670, 2024). "Current approved JAKi and those in development significantly inhibit JAK1, which is an effective therapeutic target in RA, although herpes zoster reactivation is probably a class effect of JAK1 inhibitors." (PMID 30508136, 2019). "The JAK1i group exhibited higher rates of acne, folliculitis, viral warts, and herpes zoster than the IL-13Ab group, reflecting the broader immunosuppressive effects of JAK1 inhibition, including impaired type I and II interferon signaling crucial for antiviral defense." (PMID 40861471, 2025). "Compared with pan-JAK inhibitors such as tofacitinib, the JAK1 selectivity of UPA may reduce off-target effects; however, safety concerns remain, including an increased risk of herpes zoster (particularly in Asian populations), liver enzyme abnormalities, and potential cardiovascular events." (PMID 41924137, 2026). "Reactivation of herpes zoster appears to be a class effect and may be due to inhibition of IFN and IL-15, which are key anti-viral cytokines that signal through JAK1, JAK2 and JAK3." (PMID 30508136, 2019).
liver cancer (10 papers, 2019 to 2025). An epithelial or non-epithelial malignant neoplasm that arises from the liver. "The formation of aristolactam–DNA adducts induced significant A>T transversions in TP-53 and JAK1 genes, and initiated liver cancer both in mouse and human liver cancer models." (PMID 34899315, 2021). "To identify the active ingredients for JAK1 inhibition in liver cancer, we analyzed the literature concerning the use of natural products and TCM for the treatment of liver cancer and searched for the main active components using data mining and network pharmacology." (PMID 39744421, 2025). "JAK1 and JAK2 expression were markedly higher in liver cirrhosis tissues (n = 22), while highest in liver cancer tissues (n = 53) compared to normal liver tissues (n = 5)." (PMID 35382859, 2022).
atherosclerosis (9 papers, 2018 to 2025). A disease characterized by the build-up of fatty material and calcium deposition in the arterial wall resulting in partial or complete occlusion of the arterial lumen. "The silencing of ROR ameliorates atherosclerosis progression by the inhibition of miR-26, NF-κB and JAK1/STAT3 signaling." (PMID 35407662, 2022). "Collectively, knockdown of lnc-KCNC3-3:1 alleviates the symptom of atherosclerosis via downregulation of JAK1/STAT3 pathway." (PMID 34540913, 2021). "All these results suggested that knockdown of lnc-KCNC3-3:1 alleviates development of atherosclerosis via downregulation of JAK1/STAT3 signaling pathway." (PMID 34540913, 2021). "Taken together, knockdown of lnc-KCNC3-3:1 alleviates the development of atherosclerosis via downregulation of JAK1/STAT3 signaling pathway." (PMID 34540913, 2021). "LXN deficiency stimulates the JAK1/STAT3/ABC transporter pathway, thereby enhancing the anti-inflammatory and anti-oxidant phenotype, cholesterol efflux, subsequently minimizing foam cell formation and atherosclerosis." (PMID 39424784, 2024). "We verified 4 genes of them to have a strong correlation with CAD, and IL13RA1 might participate in the inflammation, fibrosis, and cholesterol efflux process of atherosclerosis by regulating JAK1/STAT3 pathway." (PMID 36064568, 2022). "Similarly, miR-9 was involved in suppression of inflammatory responses in atherosclerosis, wherein miR-9 inhibited the activation of the NLRP3 inflammasome, and thus attenuated atherosclerosis-related inflammation through the JAK1/STAT signaling pathway." (PMID 32765295, 2020). "Consistent to in vitro data, the expressions of p-Akt, p-JAK1 and p-STAT3 in tissues of mice were notably increased in atherosclerosis group; however, these phenomena were completely reversed by lnc-KCNC3-3:1 siRNA1." (PMID 34540913, 2021). "Collectively, our data indicated that lnc-KCNC3-3:1 silencing inhibited the progression of atherosclerosis via inactivation of PI3K/Akt and JAK1/STAT3 signaling pathways." (PMID 34540913, 2021). "ROR upregulates miR-26, NF-κB and JAK1/STAT3 pathways, involved in the atherosclerosis process." (PMID 35407662, 2022). "Animal study revealed that knockdown of lnc-KCNC3-3:1 alleviated the symptom of atherosclerosis, and it could inhibit the expressions of p-JAK1, p-STAT3 and p-Akt in tissues of atherosclerosis mice." (PMID 34540913, 2021).
B-cell lymphoma (9 papers, 2015 to 2025). "With growing clinical experience, concerns about infectious complications, and increased risk of B-cell lymphoma, presumably caused by the effects of JAK1/2 inhibition on immune response and immunosurveillance, have been raised." (PMID 31788449, 2019). "A phase 1 dose-escalation/expansion study evaluated the safety and efficacy of dezapelisib, a new selective PI3Kδ inhibitor, as monotherapy or in combination with itacitinib, a selective JAK1 inhibitor, in adult patients with relapsed B-cell lymphomas." (PMID 38807597, 2024). "ChIP-seq has recently been used to study the genomic effects of nuclear JAK1 in an autocrine IL-6 and IL-10 activated B-cell lymphoma." (PMID 31275057, 2019). "Signaling downstream of IL6 and IL10 in B-cell lymphoma involves primarily activation of JAK1/JAK2-STAT3 axis and to a lesser extend the JAK1/JAK2-STAT1 or TYK2-MAPK-STAT1 axis." (PMID 26654227, 2015). "Specifically, it was shown that JAK1 regulated the expression of almost 3,000 genes in a B-cell lymphoma cell line (ABC DLBCL), with the interesting finding that many of these same genes showed phosphorylation of tyrosine 41 at histone H3, H3pY41, in the surrounding chromatin." (PMID 31275057, 2019). "Moreover, a phase I study evaluating the safety and efficacy of the novel JAK1 inhibitor INCB039110 has been recently started in relapsed/refractory B-cell lymphoma, including DLBCL (NCT01905813)." (PMID 26654227, 2015). "JAK1_8709 targets JAK1/JAK2, studies have established an excellent efficacy on treating B‐cell lymphoma with anti‐JAK management." (PMID 39811936, 2025). "Several clinical phase I/II studies, evaluating the safety and efficacy of JAK1 and JAK2 inhibitors in patients with relapsed/refractory B-cell lymphoma, including DLBCL are ongoing (NCT01905813, NCT01431209) or in planning." (PMID 26654227, 2015). "As JAK1 and JAK2 modulate epigenetic regulation of gene transcription through tyrosine phosphorylation of the histone protein H3 in leukemic- and B cell lymphoma- cell lines, we performed in vitro kinase assays to address whether JAK3 was also able to phosphorylate Histone H3." (PMID 33466582, 2021).
cervical cancer (9 papers, 2016 to 2024). A primary or metastatic malignant neoplasm involving the cervix. "Then, we tested the direct regulation of JAK1 and STAT3 exerted by miR-30a and miR-34c, respectively, and validated its effect on the proliferation rates of the cervical cancer cell lines." (PMID 38891028, 2024). "In cervical cancer cell lines, PTPRJ inactivates the Janus kinase 1 (JAK1)/STAT3 pathway, impeding proliferation and tumor formation." (PMID 38999976, 2024). "Previous data from our group had shown that IL6R, JAK1/JAK2, and STAT3/STAT5b were dysregulated in locally advanced cervical cancer." (PMID 38891028, 2024). "We validated the interactions of miR-30a and miR-34c with JAK1 and STAT3, respectively, through dual-luciferase and expression assays in cervical carcinoma-derived cell lines." (PMID 38891028, 2024). "The JAK1 and JAK3 responses in cervical cancer cells are different from the responses reported for normal lymphocytes." (PMID 27293315, 2016). "The characteristics of constitutive JAK3 phosphorylation and the lack of JAK1 phosphorylation in cervical cancer cells have been previously documented in transformed and malignant lymphocytes." (PMID 27293315, 2016). "JAK3 alone may be capable of initiating the signals induced by IL-2 even if JAK1 is not activated in cervical cancer cells." (PMID 27293315, 2016). "EPOR is expressed in cervical cancer, and the binding of erythropoietin (Epo) to its receptor induced cell proliferation; such cell response was related to the activation of JAK2, JAK3, STAT3, and STAT5, but not JAK1 and STAT1 in cervical cancer." (PMID 37372319, 2023).
chronic GVHD (9 papers, 2020 to 2025). "Recent insights into the mechanisms have unveiled new treatment targets, with ruxolitinib, a selective JAK1/2 inhibitor, emerging as a promising and safe therapy for chronic graft-versus-host disease patients." (PMID 40354779, 2025). "The introduction of ruxolitinib, a selective JAK1/2 inhibitor, has transformed the treatment landscape for steroid-refractory acute and chronic GVHD, leading to improved response rates and durable symptom control." (PMID 40722603, 2025). "Janus kinase (JAK1/2) inhibition is now regarded as a therapeutic strategy for severe acute and chronic GVHD; it seems to be effective both as acute GVHD prophylaxis, in the treatment of steroid-refractory GVHD, and in salvage therapy for chronic GVHD." (PMID 35566660, 2022). "Ruxolitinib is a selective JAK1/JAK2 inhibitor, that has been recommended as a primary treatment in steroid-refractory chronic GVHD." (PMID 39478870, 2024). "In retrospective studies, ruxolitinib, a selective Janus kinase 1/2 inhibitor as well as extracorporeal photopheresis (ECP) could show high efficacy in treatment of steroid refractory acute and chronic GVHD." (PMID 32447349, 2020). "Ruxolitinib (Jakafi®) (Incyte Corporation, Wilmington, DE, USA) is a selective JAK1/2 inhibitor, was the first agent approved by the U.S. Food and Drug Administration (FDA) for the treatment of steroid-refractory acute GVHD (aGVHD) in 2019 and chronic GVHD (cGVHD) in 2021." (PMID 40722603, 2025).